RBM15 (RNA binding motif protein 15)
Diseases named in the same sentence as RBM15 in open-access papers (continued):
Sharing a sentence is not in itself a finding about the gene and the disease.
COVID-19 (5 papers, 2021 to 2024). A disease caused by infection with severe acute respiratory syndrome coronavirus 2. "In the context of disease severity, an association was made between the levels of the m6A methyltransferase RBM15 and the severity of COVID-19, proposing RBM15 as a potential target for reducing the pathological effects of the virus." (PMID 38539075, 2024). "Future studies are warranted to explore methods for inhibiting RBM15 expression, with the aim of identifying new treatment strategies for COVID-19." (PMID 34301919, 2021). "Some of DEGs may be associated with the varying severity of COVID-19, such as METTL3, FTO, and RBM15." (PMID 35655464, 2022). "In conclusion, this study identified RBM15 regulates the expression of multitarget genes by elevating m6A modification levels, aggravates the inflammatory response, and promotes cell death signaling pathways in COVID-19." (PMID 34301919, 2021). "RNA-binding motif protein 15 (RBM15) overexpression was detected in patients with COVID-19." (PMID 34301919, 2021). "Considering that more mRNA genes were hypermethylated in patients with COVID-19, we validated that the m6A writer RBM15 was highly expressed in severe COVID-19 patients, having a critical role in modulating the balance of m6A modifications and having important functions in patients with COVID-19." (PMID 34301919, 2021). "We observed that RBM15B, HNRNPA2B1, and VIRMA may be protective factors in the development of COVID-19, and the opposite performance was found in ELAVL1, RBM15, FMR1, IGFBP3, and METTL3." (PMID 35655464, 2022).
laryngeal carcinoma (5 papers, 2021 to 2025). Carcinoma that arises from the laryngeal epithelium. "Combining with the proteomics results of laryngeal cancer tissue, the RBM15 that were differentially expressed in m6A methyltransferase “writers” was screened out as the most significant." (PMID 33637103, 2021). "The results suggested that in these measured laryngeal cancer cell lines, the expression level of RBM15 was more significant than in NHBEC cells." (PMID 33637103, 2021). "For instance, as a ‘writer’ of m6A modified way, RBM15 could facilitate proliferation and migration of laryngeal carcinoma cells by modifying TMBIM6 in laryngeal carcinoma." (PMID 36734243, 2023).
liver cancer (5 papers, 2022 to 2025). An epithelial or non-epithelial malignant neoplasm that arises from the liver. "RBM15 promotes the growth and migration of liver cancer cells and increases cancer cell growth, colony formation, invasion, and epithelial-mesenchymal transition." (PMID 40435202, 2025). "In summary, RBM15 drives HCC progression by enhancing angiogenesis through VEGFA stabilization and by mediating HBx-induced circRNA degradation, collectively establishing RBM15 as both a tumor promoter and a potential therapeutic target in liver cancer." (PMID 41403702, 2025). "The expression levels of RBM15 and RBM15B are closely linked to prognosis, immune evasion mechanisms, and resistance to immunotherapy in liver cancer patients." (PMID 39911396, 2025). "Inhibiting the expression of RBM15 and RBM15B has been shown to restore the immune system’s capacity to recognize and effectively target liver cancer cells, thus enhancing the therapeutic efficacy of immune therapies." (PMID 39911396, 2025). "As such, both RBM15 and RBM15B represent promising therapeutic targets for liver cancer immunotherapy." (PMID 39911396, 2025). "Such interventions could provide a novel approach for overcoming resistance to immune checkpoint inhibitors, making RBM15 and RBM15B inhibition a potentially effective strategy to improve liver cancer treatment outcomes." (PMID 39911396, 2025).
melanoma (5 papers, 2020 to 2024). A malignant, usually aggressive tumor composed of atypical, neoplastic melanocytes. "Nonetheless, the role of Rbm15 on melanoma cells remains understudied." (PMID 39339213, 2024). "RBM15, VIRMA, IGF2BP3, and YTHDF3 were frequently overamplified in melanoma patients, while VIRMA displayed missense mutations with unknown significance." (PMID 34446007, 2021). "Comparing primary melanoma and metastases, we found that ALKBH5, ELAVL1, FMR1, HNRNPA2B1, HNRNPC, IGF2BP1/2/3, KIAA1429, LRPPRC, RBM15, YTHDC1/2, YTHDF1/3, and ZC3H13 were significantly upregulated in metastases, while RBM15B and METTL3 were significantly upregulated in primary melanoma." (PMID 34993195, 2021).
Insulin resistance (4 papers, 2023 to 2025). Increased resistance towards insulin, that is, diminished effectiveness of insulin in reducing blood glucose levels. "Interestingly, RBM15 was recently associated with liver insulin resistance through epigenetic regulation." (PMID 40482643, 2025). "For example, RBM15 was observed to hinder insulin sensitivity and promote insulin resistance through m6A-mediated epigenetic suppression of CLDN4 during the development of gestational diabetes mellitus." (PMID 38765115, 2024). "In vitro, RBM15 suppressed insulin sensitivity and increased insulin resistance through m6A-regulated epigenetic inhabitation of CLDN4." (PMID 36803098, 2023). "Our study revealed the essential role of RBM15 in insulin resistance and the effect of RBM15-regulated m6A modification in the metabolic syndrome of offspring of GDM mice." (PMID 36803098, 2023). "In this study, our data firstly revealed that RBM15 might contribute to the development of metabolic syndrome based on insulin resistance through the m6A-mediated regulation of CLDN4 in GDM offspring." (PMID 36803098, 2023).
Obesity (4 papers, 2021 to 2022). Accumulation of substantial excess body fat. "Similar to RBM15, HNRNPC, and HNRNPA2B1, MYC expression level significance was also negatively related to obesity." (PMID 36120320, 2022).
colon adenocarcinoma (3 papers, 2025). "In colon adenocarcinoma (COAD), RBM15 expression is markedly elevated and contributes to tumor progression." (PMID 41403702, 2025). "In the Cancer Genome Atlas (TCGA)-Colon adenocarcinoma (COAD) dataset, RBM15 RNA showed the second strongest inverse correlation with immune cell infiltration levels." (PMID 40370450, 2025).
myeloid leukemia (3 papers, 2017 to 2023). A clonal proliferation of myeloid cells and their precursors in the bone marrow, peripheral blood, and spleen. "RBM15, another component of the m6A writer complex, is also linked to myeloid leukemia." (PMID 28081722, 2017). "Furthermore, we found that this RBFOX2/m6A/RBM15/YTHDC1/PRC2 axis plays a critical role in myeloid leukaemia." (PMID 37640841, 2023). "To better characterize how RBFOX2 regulates myeloid leukaemia via m6A, we correlated the expression changes of the genes co-occupied by RBFOX2 and RBM15 in either RBFOX2 KD or RBM15 KD K562 cells, and found a positive correlation, as expected." (PMID 37640841, 2023).
sarcoma (3 papers, 2022). A usually aggressive malignant neoplasm of the soft tissue or bone. "In a study of sarcomas, seven proteins related to overall survival (AMPKALPHA, CHK1, S6, ARID1A, RBM15, ACETYLATUBULINLYS40, and MSH6) were discovered using the proteomics data of different sarcoma subtypes." (PMID 35875106, 2022).
thyroid cancer (3 papers, 2021 to 2022). "We derived a three m6A RNA modification regulator genes-based risk signature (FTO, RBM15 and KIAA1429), that is an independent prognostic biomarker in patients with thyroid carcinoma." (PMID 34281544, 2021). "In addition, we proved that RBM15 functions as oncogene in thyroid cancer via PI3K-AKT-mTOR signaling pathway." (PMID 34281544, 2021). "In addition, we constructed a risk signature by using 3 m6A RNA methylation regulators (FTO, RBM15, and KIAA1429) and the risk score is an independent prognostic biomarker in patients with thyroid carcinoma." (PMID 34281544, 2021). "Immunohistochemistry result revealed that the staining intensity of 3 genes (RBM15, FTO, and KIAA1429) were higher in thyroid cancer tissue than in benign thyroid nodule tissue in our specimens which is consistent with bioinformatic analysis." (PMID 36389678, 2022). "In our study, we first verify the effect of FTO, RBM15 and KIAA1429 on the progression of thyroid carcinoma in vitro." (PMID 34281544, 2021). "High expression of RBM15 (HR = 4.341, 95% CI = 1.328–14.192, P = 0.015), FTO (HR = 1.623, 95% CI = 1.021–2.580, P = 0.041) and KIAA1429 (HR = 1.925, 95% CI = 1.079–3.434, P = 0.026) had a poor overall survival in patients with thyroid carcinoma." (PMID 34281544, 2021).
Down syndrome (2 papers, 2012 to 2022). "We report here that Setd1b interacts specifically with both Rbm15 and the leukemogenic Rbm15-Mkl1 fusion protein that is frequently found in non-Down syndrome pediatric AMKL." (PMID 22927943, 2012).
esophageal squamous cell carcinoma (2 papers, 2023 to 2025). Esophageal squamous cell carcinoma (ESCC) is a type of esophageal carcinoma (EC) that can affect any part of the esophagus, but is usually located in the upper or middle third. "In esophageal squamous cell carcinoma (ESCC), RBM15 interacts with METTL3 in a WTAP-dependent manner to deposit m6A on LncMALAT1." (PMID 36854773, 2023). "RBM15 also modulates procollagen-lysine,2-oxoglutarate 5-dioxygenase 3 (PLOD3), enhancing tumor-infiltrating CD4+ T cell abundance in esophageal squamous cell carcinoma (ESCC), correlating with favorable prognosis in ESCC4." (PMID 40370450, 2025).
glioblastoma (2 papers, 2021 to 2023). The most malignant astrocytic tumor (WHO grade IV). "Recent studies have reported that RBM15 assists ZC3H13 in regulating m6A methylation, which is essential for speeding up the progress of glioblastoma multiforme (GBM)." (PMID 33643384, 2021).
liver failure (2 papers, 2020 to 2021). A liver disease characterized by the liver losing or has lost all of its function. "Liver failure caused by rbm15 mutation also showed abnormal mTORC1 activation." (PMID 32518161, 2020).
liver fibrosis (2 papers, 2024 to 2025). "AMKL patients accompanied by RBM15::MRTFA are highly likely to be complicated with liver fibrosis, and these patients are almost all female." (PMID 40547921, 2025). "We reviewed nine cases of RBM15::MRTFA AMKL with liver fibrosis, noting that this condition predominantly affects female infants and is associated with generally poor outcomes." (PMID 39281382, 2024). "The median age of the subgroup with liver fibrosis was 6 weeks, which was lower than the median age of 4–8 months reported in larger groups of RBM15::MRTFA AMKL." (PMID 39281382, 2024). "Notably, the cases of RBM15::MRTFA with liver fibrosis seemed to occur almost exclusively in female patients (eight of nine cases)." (PMID 39281382, 2024). "Although the outcome of RBM15::MRTFA is reportedly similar to that of other patients with childhood AML, we noted a poor outcome with early death in five of nine (56%) patients with liver fibrosis." (PMID 39281382, 2024).
triple-negative breast carcinoma (2 papers, 2024 to 2025). An invasive breast carcinoma which is negative for expression of estrogen receptor (ER), progesterone receptor (PR), and human epidermal growth factor receptor 2 (HER2). "In this study, we found that the expression of the RNA-binding motif protein 15 (RBM15) m6A writer was significantly upregulated in triple-negative breast cancer (TNBC) cells and was closely associated with clinical outcomes." (PMID 38825643, 2024). "This suggests that targeting RBM15 can be new therapeutic approaches for triple-negative breast cancer patients." (PMID 38825643, 2024).
Allergy (1 paper, 2022). An allergy is an immune response or reaction to substances that are usually not harmful. "Several top-ranking genetic perturbagens including PAK1, GSR, RBM15 and TNFRSF12A have been indicated by previous studies to be involved in allergy/asthma." (PMID 35606385, 2022).
aortic aneurysm (1 paper, 2024). A ruptured aneurysm located in the wall of the proximal portion of the descending aorta proceeding from the arch of the aorta. "In our study, we successfully established an AD model in SD rats and found that RBM15 knockdown mitigated the development of aortic aneurysms." (PMID 39113895, 2024). "Aortic aneurysm formation was significantly reduced in the AD+sh-RBM15 group." (PMID 39113895, 2024). "Moreover, in vivo knockdown of RBM15 led to an amelioration of aortic aneurysm in the rat AD model." (PMID 39113895, 2024).
aortic coarctation (1 paper, 2024). "To investigate the expression and significance of RBM15 in aortic coarctation, we retrieved the microarray dataset GSE52093 from the GEO database, comprising gene expression profiles of aortic coarctation (n=7) and controls (n=5), and conducted bioinformatic analysis." (PMID 39113895, 2024).
autoimmune disease (1 paper, 2015). A disorder resulting from loss of function or tissue destruction of an organ or multiple organs, arising from humoral or cellular immune responses of the individual to their own tissue constituents. "At least seven of these are involved in autoimmune diseases or immune cell function: Ptpn22, Adora3, Rbm15, Lrig2, Cd53, Nras, and a cluster of six chitinase-like genes." (PMID 26438525, 2015).
blood disease (1 paper, 2018). A disease that occurs in the blood. "The possibility that RBM11 modulates the splicing of CCND1, and an array of oncogenic genes in EWS, is consistent with known roles for related RNA binding proteins (RBM), including RBM10, RBM15 and RBM25, which alter gene splicing to promote various forms of blood disease and cancer." (PMID 30093970, 2018).
breast diseases (1 paper, 2022). "Studies have also shown that estrogen can independently increase the expression of the RBM15 gene and is associated with the occurrence of breast diseases." (PMID 36389678, 2022).
breast tumor (1 paper, 2024). "We also confirmed that RBM15 expression was significantly greater in breast tumor tissues than in normal tissues." (PMID 38825643, 2024).
colorectal tumor (1 paper, 2025). "Specifically, RBM15 deficiency significantly delayed colorectal tumor growth by enhancing immune cell infiltration, potentially due to reduced fumarate levels within the tumor microenvironment." (PMID 40370450, 2025).
diabetes (1 paper, 2021). "We found 15 differentially-expressed genes among 20 RNA m6A methylation regulators, including EIF3C, FTO, METTL3, RBM15, etc; and 40 differentially-expressed genes among 46 diabetes related factors." (PMID 34084770, 2021).
endometrial adenocarcinoma (1 paper, 2021). "For writers, the expression of METTL3 and RBM15/15B was significantly increased in patients with endometrial adenocarcinoma versus controls." (PMID 34149936, 2021). "GEO dataset also verified the differential expression of FTO and RBM15 between patients with endometrial adenocarcinoma and hyperplasia." (PMID 34149936, 2021). "The decreased FTO expression and increased RBM15 expression in endometrial adenocarcinoma from our validation cohort was consistent with in silico analysis using TCGA and GEO datasets." (PMID 34149936, 2021). "Hence, our results provided a potential mechanism and network for the regulation of FTO and RBM15 to the progression of endometrial adenocarcinoma." (PMID 34149936, 2021). "From TCGA and GEO datasets, we found that FTO and RBM15 might take critical roles in the prognosis of endometrial adenocarcinoma." (PMID 34149936, 2021). "In the present research, we elucidated that m6A RNA methylation regulators, especially FTO, RBM15, and YTHDF1, were likewise closely related with prognosis of endometrial adenocarcinoma." (PMID 34149936, 2021). "In conclusion, m6A methylation regulators, especially FTO, RBM15, and YTHDF1, are critical in the progression and prognosis of endometrial adenocarcinoma." (PMID 34149936, 2021). "We found that METTL3 and FTO mRNA expression was evidently decreased in endometrial adenocarcinoma while RBM15 mRNA expression was increased with no changes in YTHDF1 expression in cases versus controls." (PMID 34149936, 2021). "Finally, we validated the mRNA expression of METTL3, FTO, RBM15, and YTHDF1 in clinical samples of endometrial tissues from endometrial adenocarcinoma patients and controls." (PMID 34149936, 2021). "Moreover, we also validated the roles of FTO and RBM15 in the prognosis of endometrial adenocarcinoma using the GEO dataset and predicted the possible target genes and biological processes of FTO and RBM15, which might contribute to the regulation of these two genes to endometrial adenocarcinoma." (PMID 34149936, 2021). "Hence, FTO, RBM15, and YTHDF1 may regulate the RNA processing and translation of target genes involved in the cell cycle, thermogenesis and other pathways, leading to the tumor process and prognosis of endometrial adenocarcinoma." (PMID 34149936, 2021).
endometrial cancer (1 paper, 2021). Primary or metastatic malignant neoplasm involving the endometrium (mucous membrane that lines the endometrial cavity). "FTO, RBM15, and YTHDF1, were identified as independent prognostic markers and closely associated with International Federation of Gynecology and Obstetrics grade in endometrial cancer patients." (PMID 34149936, 2021).
epilepsy (1 paper, 2022). A brain disorder characterized by episodes of abnormally increased neuronal discharge resulting in transient episodes of sensory or motor neurological dysfunction, or psychic dysfunction. "The random forest (RF) model was applied to the screening, and seven m6A regulators (HNRNPC, WATP, RBM15, YTHDC1, YTHDC2, CBLL1, and RBMX) were selected as the candidate genes for predicting the risk of epilepsy." (PMID 36468034, 2022). "We found a positive correlation between the expression of HNRNPC, RBMX, and RBM15 in patients with epilepsy." (PMID 36468034, 2022). "Firstly, we analyzed the expression of 17 m6A-related genes extracted from a public dataset and found that seven of them (HNRNPC, WTAP, RBM15, YTHDC1, YTHDC2, CBLL1, and RBMX) were differentially expressed between patients with epilepsy and healthy individuals." (PMID 36468034, 2022).
head and neck cancer (1 paper, 2021). A primary or metastatic malignant neoplasm affecting the head and neck. "It was found that head and neck cancer samples with high expression of writer genes KIAA1429 were in positive correlation with eraser genes ALKBH3 and FTO, while tumors with a high expression of writer genes (RBM15, RBM15B, and CBLL1) exhibited a low expression of eraser genes (ALKBH3 and FTO)." (PMID 35198565, 2021).
ischemia (1 paper, 2023). A hypoperfusion of the BLOOD through an organ or tissue caused by a PATHOLOGIC CONSTRICTION or obstruction of its BLOOD VESSELS, or an absence of BLOOD CIRCULATION. "In addition, qRT-PCR and Western blotting also confirmed that the expression of METTL16 and LRPPRC was downregulated and the expression of RBM15 was upregulated after ischemia." (PMID 37139237, 2023).
mastitis (1 paper, 2025). Inflammation of breast tissue during lactation or postpartum due to an obstructed duct or infection. "Likewise, RBM15 was revealed as a potential candidate gene for clinical mastitis resistance." (PMID 40660125, 2025).
megakaryoblastic leukemia (1 paper, 2012). "How the Rbm15-Mkl1 fusion protein specifically induces megakaryoblastic leukemia is not clear." (PMID 22927943, 2012).
mesenchymal tumor (1 paper, 2025). "In conclusion, AML with RBM15::MRTFA(MKL1) fusion can initially present as a soft tissue lesion in children and may lead to misdiagnosis of the malignant mesenchymal tumor." (PMID 38374236, 2025).
myeloid sarcoma (1 paper, 2025). A tumor mass composed of myeloblasts or immature myeloid cells. "Based on these findings, myeloid sarcoma/AML with RBM15::MRTFA(MKL1) fusion diagnosis was made." (PMID 38374236, 2025). "There are a few reported cases of myeloid sarcoma related to AML with RBM15::MRTFA(MKL1) fusion in the literature, which mimic non-hematologic malignancies like neuroblastoma, hepatoblastoma, or small round blue cell tumor, thus the differential diagnosis may be challenging." (PMID 38374236, 2025).